RNF183 (ring finger protein 183)
Description:
Acts as an E3 ubiquitin ligase catalyzing the covalent attachment of ubiquitin moieties onto substrate proteins. Triggers apoptosis in response to prolonged ER stress by mediating the polyubiquitination and subsequent proteasomal degradation of BCL2L1. May collaborate with FATE1 to restrain BIK protein levels thus regulating apoptotic signaling. Mediates the ubiquitination and subsequent lysosomal degradation of ATP1B1 (By similarity).
Synonyms: MGC4734
Tractability: Antibody: UniProt predicts a signal peptide or a membrane-spanning region. PROTAC: UniProt records ubiquitination sites on it.
Gene: Protein-coding gene on chromosome 9 (113,297,093 to 113,303,376, reverse strand). Ensembl gene ENSG00000165188.
Subcellular location: Endoplasmic reticulum membrane; Endoplasmic reticulum; Golgi apparatus, cis-Golgi network membrane; Lysosome membrane
Gene Ontology:
Molecular function: protein binding; ubiquitin protein ligase activity
Biological process: positive regulation of endoplasmic reticulum stress-induced intrinsic apoptotic signaling pathway; protein autoubiquitination; protein polyubiquitination; response to endoplasmic reticulum stress; protein ubiquitination
Cellular component: endoplasmic reticulum; endoplasmic reticulum membrane; cis-Golgi network membrane; lysosomal membrane; plasma membrane; Golgi apparatus
Genetic constraint (gnomAD): Loss-of-function variants: 7 observed, 11.05 expected, observed/expected ratio (o/e) 0.63, 90% interval 0.36 to 1.19. The upper end of that interval is the gene's LOEUF score, 1.19, which puts it in group 5 of 6, group 1 being the genes least tolerant of losing a copy. Missense variants: 227 observed, 263.24 expected, observed/expected ratio (o/e) 0.86, 90% interval 0.77 to 0.96. Synonymous variants: 102 observed, 111.22 expected, observed/expected ratio (o/e) 0.92, 90% interval 0.78 to 1.08.
Homologues: Orthologues: chimpanzee RNF183 (98% identical), macaque RNF183 (94% identical), dog RNF183 (89% identical), mouse Rnf183 (88% identical), rabbit RNF183 (86% identical), rat Rnf183 (86% identical), guinea pig RNF183 (85% identical), pig RNF183 (85% identical), tropical clawed frog rnf183 (46% identical). Paralogues in human: RNF223 (29% identical), RNF225 (26% identical), RNF208 (17% identical).
Diseases named in the same sentence as RNF183 in open-access papers:
RNF183 is named in the same sentence as 19 diseases in open-access papers, as found by Europe PMC text mining. Sharing a sentence is not in itself a finding about the gene and the disease. The quoted sentences say what the papers report.
colorectal cancer (8 papers, 2017 to 2026). A primary or metastatic malignant neoplasm that affects the colon or rectum. "Reversal of the apoptosis defects caused by FBXO5 deficiency in colorectal cancer cells can be achieved by knocking down RNF183 in FBXO5-deficient cells." (PMID 38212299, 2024). "While RNF43 and RNF183 have been previously implicated in colorectal cancer progression, the consistent and significant elevation of RNF39, a comparatively understudied member of this protein family, suggests it may function as a novel and distinct regulator in COAD pathogenesis." (PMID 41457280, 2026). "Our study indicated that RNF38 exhibited a negative effect on growth and metastasis in NPC by suppressing NF-κB and MAPK activation instead of activating the NF-κB pathway by RNF20 or RNF183 in colorectal cancer." (PMID 35568845, 2022). "RNF183 has been reported to occur in diverse diseases such as colorectal cancer (CRC), kidney disease, inflammatory bowel disease and various biological processes." (PMID 33324448, 2020). "Similarly, RNF183 also contributes to the carcinogenesis of colorectal cancer, similar to RNF6." (PMID 35568845, 2022).
inflammatory bowel disease (7 papers, 2017 to 2025). A spectrum of small and large bowel inflammatory diseases of unknown etiology. "The expression of RNF183 was found to be up-regulated in inflammatory bowel disease (a causative factor for CRC) and to activate the classical nuclear factor-kappaB (NF-κB) pathway." (PMID 28756770, 2017). "Although RNF183 is found upregulated in inflammatory bowel disease (IBD), a disease highly associated with CRC, and activates classic NF-κB pathway, its role in cancer cells remains largely unknown." (PMID 28796265, 2017). "Since the abundance of RNF183-targeted shRNA was significantly decreased in the trametinib group (P < 0.05), and since it has been reported to play an important role in inflammatory bowel disease, which is a causative factor of CRC, we selected this gene for further experiments." (PMID 28756770, 2017). "Altered expression of RNF183 has been associated with a range of diseases, including CKD and inflammatory bowel disease, as well as various cellular processes, such as apoptosis and endoplasmic reticulum stress." (PMID 40072093, 2025). "Another study demonstrated that RNF183 expression is strongly upregulated in inflamed colon samples from patients with inflammatory bowel disease." (PMID 29300766, 2018). "It was reported that RNF183 activated the NF-κB pathway in inflammatory bowel disease, so we investigated whether downstream target genes of the NF-κB pathway were required for the function of RNF183." (PMID 28756770, 2017). "RNF183 is a ubiquitin ligase containing RING-finger and transmembrane domains, and its expression levels are increased in patients with inflammatory bowel disease (IBD), including Crohn’s disease and ulcerative colitis, and in 2,4,6-trinitrobenzene sulfonic acid-induced colitis mice." (PMID 31889078, 2019).
endometrial cancer (4 papers, 2017 to 2023). Primary or metastatic malignant neoplasm involving the endometrium (mucous membrane that lines the endometrial cavity). "We found that RNF183 seems to be a new marker associated with ERα in ERα-positive endometrial cancer." (PMID 33324448, 2020). "Similarly for RNF183, its association with ERα may be a marker in ERα-positive endometrial cancer." (PMID 35163161, 2022). "Expression of TMEFF2 and BTG anti-proliferation factor 1 (BTG1) was lower in primary endometrial cancer compared to the healthy endometrium, while significant overexpression was noted for ring finger protein 183 (RNF183)." (PMID 35163161, 2022). "In the case of RNF183, the analysis showed its high level in endometrial cancer compared to normal endometrium, which is consistent with the previously used tools." (PMID 35163161, 2022). "We clarify a character for RNF183 in promoting ERα expression at the transcript and protein level in endometrial cancer." (PMID 33324448, 2020). "To investigate the role of RNF183 in endometrial cancer, we utilized UALCAN website to assess RNA-seq in 546 primary endometrial tumors and 35 normal endometrial tissues." (PMID 33324448, 2020). "The conclusion above made us search RNF183 expression in different subtypes and tumor grades of endometrial cancer, which results in diversification of the disease and specific clinical outcomes." (PMID 33324448, 2020). "In sum, these data indicate that ERα raises RNF183 protein stability in the ERα-positive endometrial cancer cells." (PMID 33324448, 2020). "The results of our study showed that significantly amplification of RNF183 was considered as a prognostic marker in endometrial cancer." (PMID 33324448, 2020). "Among all the cancer types, RNF183 is remarkably upregulated in endometrial cancer compared with normal endometrium." (PMID 33324448, 2020). "RNF183, a member of the E3 ubiquitin ligase, has been shown to involve in carcinogenesis and proposed as one of the biomarkers in Uterine Corpus Endometrial Carcinoma (UCEC)." (PMID 33324448, 2020). "It was proposed that RNF183 could be as one of the potential biomarkers for endometrial cancer through gene expression screening." (PMID 33324448, 2020). "Also, the RNF183 expression was greater at higher expression and the tumor stage was greater at the lower level, implying the early role of RNF183 in the development of endometrial cancer." (PMID 33324448, 2020). "Furthermore, the crosstalk between RNF183 and ERα may be the reason for the abnormally high expression of RNF183 in endometrial cancer." (PMID 33324448, 2020). "In endometrial cancer, infiltrating levels of CD8+ T cells, macrophages, and dendritic cells have also been reported to be affected by the RNF183 copy number variation." (PMID 35163161, 2022).
bladder cancer (3 papers, 2023 to 2025). "In summary, we identified a novel YTHDC1/GLUT3/RNF183 feedback loop that regulates disease progression and glucose metabolism in bladder cancer." (PMID 37258572, 2023). "Taken together, these data suggest that the GLUT3/RNF183 axis promotes YTHDC1 degradation in bladder cancer cells." (PMID 37258572, 2023). "Therefore, we identified a novel YTHDC1/GLUT3/RNF183 feedback loop that regulates disease progression and glucose metabolism in bladder cancer." (PMID 37258572, 2023). "Thus, we identified a novel YTHDC1/GLUT3/RNF183 feedback loop in bladder cancer cells." (PMID 37258572, 2023). "Meanwhile, in bladder cancer, AARS1-mediated lactylation promotes RNF183-mediated ubiquitination and the degradation of YTHDC1." (PMID 41008630, 2025). "Here, we identified a positive feedback loop, namely, YTHDC1/GLUT3/RNF183, to clarify the relationship between YTHDC1 and glucose metabolism in bladder cancer cells." (PMID 37258572, 2023). "Although the molecular mechanism by which GLUT3 upregulates RNF183 is not clear, we demonstrated that RNF183 is the key mediator through which GLUT3 destabilizes YTHDC1 in bladder cancer cells." (PMID 37258572, 2023). "Thus, we hypothesized that RNF183 might be the bridge between GLUT3 and YTHDC1 degradation in bladder cancer cells." (PMID 37258572, 2023).
colitis (3 papers, 2017 to 2021). Inflammation of the colon. "In DSS colitis mice, compared with inflammatory cytokines, RNF183 was expressed at a very early stage and specifically in epithelial cells." (PMID 31889078, 2019). "To determine when RNF183 is expressed in DSS-induced colitis, we investigated RNF183 expression at an early stage of DSS-induced colitis." (PMID 31889078, 2019). "RNF183 expression has also been induced in the mouse colon of TNBS colitis model." (PMID 31889078, 2019). "Considering these findings, RNF183 may be associated with the pathogenesis of IBD and considered to be a potential novel drug target for IBD if its involvement in colitis is demonstrated in an IBD model mouse." (PMID 31889078, 2019). "Therefore, RNF183 expressed at such an early stage of DSS-induced colitis may have an important role in the pathogenesis of IBD." (PMID 31889078, 2019). "Although RNF183 expression is extremely low in the colon, a recent study demonstrated that RNF183 expression was strongly induced in inflamed colon samples from patients with IBD and TNBS-induced colitis mice." (PMID 31889078, 2019). "Furthermore, the expression of RNF183 was up-regulated in IECs of IBD patients and TNBS-induced colitis mouse model, and promoted NF-κB signaling mediated intestinal inflammation by increasing ubiquitination -proteasome degradation of IκB." (PMID 34956195, 2021). "Here, we investigated whether RNF183 expression is induced by another IBD model mouse by using DSS and determined when and where RNF183 is expressed in a DSS colitis model." (PMID 31889078, 2019). "Similarly, RNF183 expression in colonic epithelial cells was up-regulated in IBD patients and DSS-induced colitis mouse model, leading to caspase-8 mediated apoptosis by promoting K63-linked ubiquitination-mediated lysosomal degradation of death receptor 5 (DR5)." (PMID 34956195, 2021). "On the other hand, our cell sorting and PCR analyses demonstrated that RNF183 was specifically expressed in colonic epithelial cells, but not immune cells, during DSS-induced colitis." (PMID 31889078, 2019).
ulcerative colitis (3 papers, 2019 to 2025). An inflammatory bowel disease involving the mucosal surface of the large intestine and rectum. "Moxibustion encourages the recovery of colon injury probably by regulating the expression of NLRP3 protein in ulcerative colitis rats through miR7/RNF183/NF-κB signaling pathway." (PMID 34777536, 2021). "The research aimed to investigate the influence of moxibustion on the activation of NLRP3 inflammasome and its mechanism in treating ulcerative colitis by observing miR7/RNF183 inducing IκB α ubiquitination to regulate NF-κB signaling pathway in an ulcerative colitis rat model." (PMID 34777536, 2021).
colon cancer (1 paper, 2024). "The results revealed that silencing FBXO5 resulted in a decelerated growth of colon cancer cells, while silencing RNF183 effectively reversed the growth arrest induced by FBXO5 silencing." (PMID 38212299, 2024). "Furthermore, we demonstrated that FBXO5 plays a crucial role in the progression of colon cancer by promoting the ubiquitination and degradation of RNF183, which leads to the inhibition of ER stress-induced cell apoptosis." (PMID 38212299, 2024). "Additionally, FBXO5 is found to be upregulated in colon cancer and functions by inhibiting ER stress-induced apoptosis through promoting the ubiquitination degradation of RNF183, thereby contributing to colon cancer progression." (PMID 38212299, 2024). "Therefore, our study highlights the critical role of the FBXO5/RNF183 axis in ER stress regulation and identifies a potential therapeutic target for colon cancer treatment." (PMID 38212299, 2024). "Interestingly, in colon cancer, FBXO5 is found to be overexpressed and plays a role in preventing ER stress-induced apoptosis via its ability to ubiquitinate and degrade RNF183, a critical regulator of ER stress-induced apoptosis." (PMID 38212299, 2024).
diabetes (1 paper, 2025). "In this study, we demonstrated, for the first time, that RNF183 expression in renal biopsy sections from DKD patients gradually decreased with the progression of diabetes." (PMID 40072093, 2025).
endometrioid adenocarcinoma (1 paper, 2020). An adenocarcinoma characterized by the presence of malignant glandular epithelial cells resembling endometrial cells. "Additionally, we found that RNF183 level was considerably higher in endometrioid adenocarcinomas compared to non-endometrioid adenocarcinomas." (PMID 33324448, 2020).
cancer (8 papers, 2017 to 2024). A tumor composed of atypical neoplastic, often pleomorphic cells that invade other tissues. "Currently, accumulating studies have demonstrated that RING fingers (RNFs), such as RNF43, RNF20, RNF125, RNF6, and RNF183, are significantly associated with the development of cancers." (PMID 35568845, 2022). "Previously, we reported that inhibition of Cat D sensitized cancer cells to anticancer drugs through RNF183-mediated Bcl-xL degradation, and activation of NF-κB signaling is important for the induction of RNF183 expression." (PMID 35715412, 2022). "In previous study, we reported that inhibition of Cat D sensitizes cancer cells to anticancer drugs via RNF183-mediated downregulation of Bcl-xL expression." (PMID 35715412, 2022). "Our data, therefore, suggested that the induction of RNF183 by Pep A is critical in sensitization of cancer cells to anticancer drugs through the degradation of Bcl-xL." (PMID 35121737, 2022). "Inhibition of Cat D sensitizes cancer cells to anticancer drugs via downregulation of Bcl-xL while upregulation of RNF183 plays a critical role in Bcl-xL degradation." (PMID 35715412, 2022). "Cat D inhibition sensitizes cancer cells to anticancer drugs via RNF183-mediated Bcl-xL degradation." (PMID 35715412, 2022). "Inhibition of cathepsin D (Cat D) sensitizes cancer cells to anticancer drugs via RNF183-mediated downregulation of Bcl-xL expression." (PMID 35715412, 2022). "From the TIMER database of the Diff Exp module across all the cancer genome atlas (TCGA) tumors, our studying showed that a high proportion of RNF183 exists in the majority of human cancer tissues." (PMID 33324448, 2020). "RNF183 upregulates the expression of multifunction chemokine IL-8 through NF-κB pathway and promotes cancer cell growth, migration, invasion and metastasis in vitro and in vivo." (PMID 28796265, 2017). "Understanding the function of RNF183 could lead to new therapeutic strategies for patients with IBD and various types of cancer." (PMID 32486221, 2020).